EGFR (epidermal growth factor receptor)
Diseases named in the same sentence as EGFR in open-access papers (continued):
Sharing a sentence is not in itself a finding about the gene and the disease.
glioma (continued). "For instance, anti-epidermal growth factor receptor (EGFR) and EGFR variants have been developed for treating glioma." (PMID 34839348, 2021). "Genetic mutation and amplification of the Epidermal Growth Factor Receptor (EGFR) in glioma highlight an opportunity to treat patients using EGFR tyrosine kinase inhibitors." (PMID 33920356, 2021). "Activation of ErbB receptors family (e.g., epidermal growth factor receptors; EFGR) initiates a pathway of downstream signaling in cell proliferation, which has a role in glioma progression and germline polymorphism of EGFR." (PMID 33567737, 2021). "In high TNFSF13 gliomas, somatic mutation was proved to correlate with amplification of EGFR and deletion of CDKN2A; while mutation of IDH1 was more frequently observed in low TNFSF13 group." (PMID 34712225, 2021). "In fact, detection of EGFR amplification or mutations (such as the common vIII deletion or point mutations) is associated with an increase in the aggressiveness of these gliomas, even if the histology corresponds to a grade III tumor." (PMID 32570988, 2020). "Several clinically significant molecular alterations (including mutations in IDH, 1p/19q, MGMT, and EGFR) have been described in gliomas and combined with histology for tumor classification." (PMID 33614625, 2020). "Next, to validate the potential therapeutic effects of targeting these proteins with drugs, we analyzed large-scale drug sensitivity data from 21 human glioma cell lines (including EGFR-mutated and wild-type; 13 GBM, 8 LGG; GDSC)." (PMID 32727536, 2020). "For IDH-WT glioma grading, the cIMPACT update 3 recommends the assessment of EGFR amplification, combined chromosomes 7p gain/10q loss, and TERT promoter mutation, which are established predictors of poor outcome, regardless of histology ⁠." (PMID 33059718, 2020). "It was demonstrated on cultured glioma SCs that the association of HSP90 with EGFR/EGFRvIII preserves the receptor complexes from proteasomal degradation, thus supporting the work of cancer stemness-promoting pathways." (PMID 32268506, 2020). "EGFR is amplified and/or mutated in nearly 50% of high-grade gliomas, favoring the survival of tumor cells and increasing their proliferative, angiogenic, and invasive capacities." (PMID 31947645, 2020). "Overall, compared to adult high-grade gliomas, pNMGs are less likely to have EGFR gene amplification and less likely to have mutations within the PTEN tumor suppresor gene, although correlations with prognosis and clincial significance are limited." (PMID 32903405, 2020). "EGFR variant III (EGFRvIII) is the most common EGFR mutation that was reported in up to 30% of high-grade gliomas." (PMID 32820249, 2020). "The results of our study, provide deep insight into the role of H2AZK4/7AC in glioma with EGFR variant III (EGFR‐vIII) overexpression." (PMID 31993801, 2020). "It has been proposed that genetic mutation of EGFR gene is responsible for the pathogenesis of gliomas." (PMID 33112545, 2020). "Factors including age at diagnosis, WHO grade, IDH status, MGMT promoter status, EGFR status and risk score were statistically related with the overall survival (OS) of glioma patients." (PMID 32373523, 2020). "Copy number mutations of CDKN2A and EGFR have been reported as early events in glioma development, whereas PTEN alterations have been described to occur later." (PMID 32604718, 2020).
glioma (continued). "Mutational analysis of TCGA data set revealed that SNPs in IDH1, ATRX, PTEN and EGFR were significantly associated with risk status in glioma." (PMID 32301283, 2020). "GATA2 has been directly implicated in promotion of glioma through the EGFR/ERK/Elk-1 pathway, further indicating its potential to forward tumor development in GBM." (PMID 32513296, 2020). "For example, an EGFR splice variant, lacks exon 4 (de4 EGFR), was found to constitutively activate downstream pathways to promote cancer cell proliferation and metastasis in glioma, prostate cancer, and ovarian cancer tissues." (PMID 32883335, 2020). "We designed a 14-gene NGS panel specifically aimed at the diagnosis of glioma, which allows simultaneous detection of mutations and copy number variations, including the 1p/19q-codeletion and Epidermal Growth Factor Receptor (EGFR) amplification." (PMID 31167453, 2019). "Additional studies have shown that the EGFR glioma risk variants have been associated with CDKN2B-AS1 loss and EGFR amplification." (PMID 31842352, 2019). "Here we revealed that EGFR mutation leads to an up-regulation of immune response related pathways and dismal prognosis in lower-grade glioma." (PMID 31801484, 2019). "EGFR mutation indicates increasing infiltration of specific types of immune cells and poor prognosis in lower-grade glioma." (PMID 31801484, 2019). "Glioma EVs carry the oncogenic epidermal growth factor receptor (EGFR) and its deleted variant III (EGFRvIII) protein and mRNA." (PMID 32038644, 2019). "One of the earliest oncogenes to be discovered in gliomas is the epidermal growth factor receptor (EGFR) gene, which is mutated and/or amplified in 50–60% of primary GBMs." (PMID 31505839, 2019). "In the present study, we demonstrated an immune infiltration related pattern of EGFR mutation in lower-grade glioma." (PMID 31801484, 2019). "To explore the characteristics of EGFR mutations in lower grade glioma, we performed differential analysis of gene expression using RNA-seq data from TCGA-LGG cases with and without EGFR mutations." (PMID 31801484, 2019). "A similar finding was also found in the TWAS that increased expression of EGFR was negatively associated with glioma risk." (PMID 31842352, 2019). "Amplification of EGFR is the most commonly observed genetic abnormality in glioma, and more than 50% of glioma cases are said to be associated with amplification of EGFR." (PMID 31595389, 2019). "PDGFRA-associated gliomas were enriched in oligodendrogenesis genes, EGFR-low in the signature of mature neurons and PDGFRA-low in the signature of oligodendrocytes." (PMID 30279357, 2018). "EGFR on the other hand is variably expressed on glioma cells either in its wildtype form or its mutant variant, EGFRVIII." (PMID 29914561, 2018). "For low-grade glioma cases with an actionable mutation, protein profiles of EGFR_pY1068, HER2_pY1248, HER2, IGFBP2, EGFR_pY1173, and STAT5-alpha are decreased." (PMID 30442178, 2018). "The other three groups, PDGFRA-associated gliomas and EGFR-low and PDGFRA-low gliomas, were associated with a better prognosis." (PMID 30279357, 2018).
glioma (continued). "This variant is within one of two previously identified independent glioma risk loci located near epidermal growth factor receptor (EGFR) and is most strongly associated with risk for GBM4,17." (PMID 29743610, 2018). "Mutations in epidermal growth factor receptor (EGFR) have also been encountered in glioma, and in NSC, confer a proliferative advantage and enhanced tumor cell survival." (PMID 30697499, 2018). "EGFR-associated gliomas were characterized by a poorer prognosis, and stronger expression of neural stem cell and astrogenesis genes." (PMID 30279357, 2018). "On the other hand, the presence of the A289D EGFR mutation previously associated with glioma, is a novel finding, and suggests potential utility of EGFR inhibitors in gastric cancer." (PMID 29854313, 2018). "It is of note that the A289D EGFR mutation identified in GC and RC, which represents the most common site of extracellular EGFR mutation, is frequent in human glioma." (PMID 29854313, 2018). "IDH wild-type high grade gliomas with 7p gain, 10q loss, EGFR amplification and TERT promoter mutation were considered as GBM (corresponding to WHO grade IV) (n = 146)." (PMID 29720725, 2018). "Our previous study shows that EGFRvIII stably transfected U87MG cells display hyperproliferation, mimicking the highly malignant primary gliomas with EGFR mutation and amplification." (PMID 30595797, 2018). "These bioconjugates were administered intracerebrally by means of CED to rats bearing receptor positive F98 gliomas that have been transfected with the human gene encoding EGFR or EGFRvIII (F98EGFR or F98EGFRvIII)." (PMID 29914561, 2018). "Amplification and mutation of the epidermal growth factor receptor (EGFR) represents crucial genetic signature in GSCs and mAbs directly targeting EGFR is used as a well-known therapeutic approach in glioma." (PMID 30619286, 2018). "The R-613 recombinant was designed to target EGFRvIII, a glioma-specific variant of EGFR which carries a 26 amino acid deletion in the extracellular domain." (PMID 29966356, 2018). "The aim of this study was to investigate and validate the potential relationship between tSNPs in EGFR gene and glioma susceptibility in the Han Chinese population using a case-control study." (PMID 28938685, 2017). "SPSS 19.0 statistical packages, χ2 test, genetic model analysis and SHEsis software platform were analyzed s the variants in EGFR gene associations with glioma risk." (PMID 28938685, 2017). "Epidermal growth factor receptor activation in C6 glioma cells upregulates xCT in association with increased GSH levels." (PMID 28424758, 2017). "EGFRvIII is the most common EGFR mutation, occurring concurrently with EGFR amplification in high grade gliomas." (PMID 29246031, 2017). "We successfully genotyped 8 tSNPs in EGFR and found some evidence of association at 3 SNPs (rs1468727, rs730437, and rs11506105) that were associated with glioma risk." (PMID 28938685, 2017). "The objective of this systematic review and meta-analysis is to determinate the associations of EGFR gene polymorphisms with glioma risk based on GWAS and case-control studies." (PMID 29156842, 2017). "RAS/MAPK activation in glioma has been shown to result both from constitutive activation of receptor tyrosine kinases EGFR, PDGFRA, and c-MET as well by an inactivating mutation of NF1, a suppressor of RAS GTPase activity." (PMID 28256619, 2017).
glioma (continued). "Amplification and overexpression of EGFR are observed in 50% of gliomas and associate with a worse prognosis." (PMID 28287096, 2017). "The results of genome-wide association studies (GWAS) and case-control studies performed to investigate the associations between epidermal growth factor receptor (EGFR) gene polymorphisms and glioma risk are controversial." (PMID 29156842, 2017). "Our results found that the C allele of rs1468727 and rs730437, intronic SNPs within the EGFR gene, which was associated with an increased risk of glioma compared to controls." (PMID 28938685, 2017). "Considering the frequent gain-of-function mutations of EGFR in glioma, characterization of CNSCs expressing EGFRviii is important for understanding the molecular properties of neural cancer stemness." (PMID 28830458, 2017). "As the most frequent and the most malignant glioma in the adult population, accounting for approximately 30% - 50% of high-grade glioma and containing a genetic mutation of EGFR (EGFRvIII)." (PMID 28938685, 2017). "The presence of EGFR mutations significantly promotes the invasive capacity of glioma cells through the regulation of integrin, CAMs, urokinase-type plasminogen activator/receptor (uPA/uPAR), MMPs and microRNAs." (PMID 29207533, 2017). "In multiple glioma cell lines and patient-derived glioma stem cells (GSCs), EGFR signaling promotes H3K23 acetylation and association with TRIM24." (PMID 29129908, 2017). "Both Src and Flyn (both members of SFK) associate with and are phosphorylated by EGFR in glioma cells." (PMID 28629170, 2017). "EGFR is associated with higher-grade gliomas, and its amplification and activating mutation can be accurate molecular markers in glioma subtyping." (PMID 28458684, 2017). "We further analyzed the association between EGFR tSNPs and glioma risk under five gene models (codominant, dominant, recessive, overdominant and additive)." (PMID 28938685, 2017). "First, no study was performed to detect the association between two important EGFR SNPs (rs11979158 and rs2252586) and glioma risk in Asians." (PMID 29156842, 2017). "Recent reports suggested that reduction in activation of EGFR pathway was linked to apoptosis in various cancer cells including glioma." (PMID 29029435, 2017). "In mice, EGFR-overexpressing gliomas are associated with greater invasiveness, and the xCT inhibitor sulfasalazine suppressed tumor growth and invasiveness." (PMID 28424758, 2017). "Their analysis identified rs11979158 and rs2252586 in EGFR gene played an important role in risk and development of glioma." (PMID 29156842, 2017). "Our study is an exploratory research which shed new light on the association between EGFR tSNPs and glioma risk in the Chinese population." (PMID 28938685, 2017). "Although several studies showed that EGFR gene polymorphisms were associated with glioma risk, those currently available results are inconclusive." (PMID 28938685, 2017). "EGF receptor (EGFR) amplification and mutation are major drivers in glioma tumorigenesis but this mechanism is not well understood." (PMID 29129908, 2017). "As a large percentage of gliomas display gene amplification of EGFR or gene mutation of PTEN, the PI3K/Akt pathway is activated in most of them." (PMID 28629170, 2017). "Larger glioma studies with dense tagging of the EGFR gene are required to elucidate the number of true associated genetic variants." (PMID 26839018, 2016). "Additional polymorphisms suggested to be associated with glioma risk include rs4947979 and rs4947986 at 7p11.2 (EGFR), identified by our group through a candidate gene approach." (PMID 26906551, 2016). "Postnatal PTEN loss or mutant epidermal growth factor receptor expression was also found to result in the generation of glioma in a transgenic mouse glioma model." (PMID 26993776, 2016).
glioma (continued). "In conclusion, our data indicated that age, extent of resection, chemotherapy and five different SNPs (rs11506105, rs3752651, rs1468727 rs845552 and rs730437) in EGFR were associated with the prognosis of glioma patients." (PMID 27437777, 2016). "In this study, we investigated if there is a correlation between genetic glioma risk variants and levels of EGFR and ErbB2 in pre-diagnostic sera from glioma patients and matched controls." (PMID 26906551, 2016). "Despite these limitations, the significant association between EGFR polymorphisms and prognosis in patients with glioma warrants has demonstrated its potential as a promising therapeutic target in glioma." (PMID 27437777, 2016). "Although previous association studies demonstrated that genetic polymorphisms in EGFR were associated with glioma risk, few studies focused on the effects of these alterations on glioma patient prognosis." (PMID 27437777, 2016). "Numerous studies have found an association between the expression of EGFR and its heterodimerization partner ErbB2 within different tumors, including gliomas." (PMID 26906551, 2016). "Additional studies based on larger sample sizes and patients with different ethnicities are needed to further evaluate the association between genetic polymorphisms in EGFR and the prognosis of glioma and astrocytoma patients in larger samples." (PMID 27437777, 2016). "Future studies with more precise clinicopathological data as well as functional studies are required to investigate the role of EGFR polymorphisms on glioma patient outcomes." (PMID 27437777, 2016). "Previous studies suggested that single nucleotide polymorphisms (SNPs) in epidermal growth factor receptor (EGFR) are associated with risk of glioma." (PMID 27437777, 2016). "This missing information offered a compelling rationale for our study: we investigated potential associations between known glioma risk variants and pre-diagnostic serum levels of EGFR and ErbB2." (PMID 26906551, 2016). "In this study, we examined the associations between eight different SNPs in EGFR and prognosis of a population of Chinese glioma patients." (PMID 27437777, 2016). "We retrospectively evaluated 269 glioma patients and investigated associations between EGFR SNPs and patient prognosis using Cox proportional hazard models and Kaplan-Meier curves." (PMID 27437777, 2016). "We assessed the associations between genetic glioma risk variants and serum concentrations of EGFR and ErbB2, as measured in pre-diagnostic cohort serum samples of 593 glioma patients and 590 matched cancer-free controls." (PMID 26906551, 2016). "Our study evaluated the influence of IDH1/2 mutation, 1p/19q codeletion, TERTp mutation and EGFR amplification in the prognostic value of histological grade in a cohort of 214 cases of lower-grade gliomas." (PMID 26369702, 2015). "U87-viii astrocytes associated with aggressive glioma cell proliferation express in addition a hyperactive EGFR variant III." (PMID 26617336, 2015). "The genomic architecture of EGFR amplified gliomas was much more complex, with a high number of gains and losses across the genome." (PMID 26257825, 2015). "Activation of the NF-κB complex by the mutant and constitutively active variant vIII of the epidermal growth factor receptor (EGFR) was linked to alkylator resistance in glioma cells." (PMID 25682871, 2015). "We next investigated the association of EGFR, Crk, Crk pY251 and Abi1-Iso2 protein expression in the tumor tissues with clinical and pathologic characteristics of glioma patients as previously indicated." (PMID 26473374, 2015).